PCDHA8 (protocadherin alpha 8)
Description:
Potential calcium-dependent cell-adhesion protein. May be involved in the establishment and maintenance of specific neuronal connections in the brain.
Synonyms: PCDH-ALPHA8
Tractability: Antibody: its Gene Ontology location is reachable by antibodies, with high confidence; UniProt places it where antibodies can reach, with medium confidence; UniProt predicts a signal peptide or a membrane-spanning region.
Gene: Protein-coding gene on chromosome 5 (140,841,187 to 141,012,347, forward strand). Ensembl gene ENSG00000204962.
Subcellular location: Cell membrane
Subcellular location (Human Protein Atlas): Microtubules; Plasma membrane; Cytokinetic bridge; Mitotic spindle; Primary cilium
Gene Ontology:
Molecular function: cell adhesion molecule binding; calcium ion binding
Biological process: cell adhesion; nervous system development; homophilic cell-cell adhesion
Cellular component: plasma membrane; membrane
Genetic constraint (gnomAD): Loss-of-function variants: 53 observed, 64.3 expected, observed/expected ratio (o/e) 0.82, 90% interval 0.66 to 1.04. The upper end of that interval is the gene's LOEUF score, 1.04, which puts it in group 4 of 6, group 1 being the genes least tolerant of losing a copy. Missense variants: 1,293 observed, 1,279.6 expected, observed/expected ratio (o/e) 1.01, 90% interval 0.96 to 1.06. Synonymous variants: 618 observed, 575.46 expected, observed/expected ratio (o/e) 1.07, 90% interval 1 to 1.15.
Homologues: Orthologues: mouse Pcdha6 (83% identical). Paralogues in human: PCDHA6 (91% identical), PCDHA3 (82% identical), PCDHA5 (82% identical), PCDHA11 (81% identical), PCDHA10 (81% identical), PCDHA13 (81% identical), PCDHA1 (81% identical), PCDHA4 (81% identical), PCDHA9 (80% identical), PCDHA12 (80% identical), PCDHA7 (80% identical), PCDHA2 (79% identical), and 49 more.
Diseases named in the same sentence as PCDHA8 in open-access papers:
PCDHA8 is named in the same sentence as 8 diseases in open-access papers, as found by Europe PMC text mining. Sharing a sentence is not in itself a finding about the gene and the disease. The quoted sentences say what the papers report.
depression (5 papers, 2021 to 2024). "Low Pcdha8 expression increases the risk of depression, but the influence of high Pcdha8 expression on depression is unclear." (PMID 37907907, 2023). "We found that PCDHA8 (P = 1.31 × 10−3) was significantly downregulated in depression cases compared with controls in GSE101521 dataset." (PMID 34021117, 2021). "This included genes such as SLC12A5, which showed evidence of a genetically predicted effect on depression and neuroticism (P = 7.13 × 10−10 and P = 2.10 × 10−9 respectively), as well as PCDHA8, which provided evidence of genetically predicted effect on schizophrenia risk (P = 6.04 × 10−6)." (PMID 33481009, 2021). "Several TWAS significant genes were also dysregulated in brains of depression cases compared with controls (including PCDHA8, FANCL, TMEM161B-AS1, GMPPB, STAU1, NDUFA2, GPX1 and PCDHA7), implying that genetic variants may contribute to depression risk by regulating gene expression." (PMID 34021117, 2021). "Many of these genes have been previously linked to brain-related disorders, including Alzheimer’s disease (WDR12, AGFG2, and CDK5RAP3), schizophrenia (SRA1, WDR55, CORO7, DDAH2, PCDHA8), autism spectrum disorder (MAPK3, PCDHA13), and major depressive disorder (ZMAT2 and ITIH4)." (PMID 39269986, 2024). "The overlapping eQTL genes between AD and depression (SRA1, MICA, PCDHA8, PCDHA10, PCDHA7, and PCDHA13), were not yet associated with these disorders through proximity analysis nor have an established role in these diseases as of yet." (PMID 38862462, 2024).
glioma (2 papers, 2011 to 2023). A benign or malignant brain and spinal cord tumor that arises from glial cells (astrocytes, oligodendrocytes, ependymal cells). "Inflammatory microglial cells, dendritic cells, myeloid cells, and glioma stem cells were highly expressed in GBM tissue, and ACP7, EPPK1, PCDHA8, RHOD, DRC1, ZIC3, and PRLR were significantly associated with survival." (PMID 36836422, 2023). "It is known to participate in neural cadherin-like adhesion, serving a key role in brain cell connection, and previous studies have reported that PCDHA8 is hypermethylated in gliomas." (PMID 36836422, 2023). "Eight promoter-hypermethylated genes (ANKDD1A, GAD1, HIST1H3E, PCDHA8, PCDHA13, PHOX2B, SIX3, and SST) were confirmed in primary glioma and cell lines." (PMID 21962230, 2011). "The methylation levels of seven gene promoters (ANKDD1A, GAD1, SIX3, SST, PHOX2B, PCDHA8, and HIST1H3E) in glioma patients and cell lines were significantly higher than those in non-tumor controls (p < 0.01)." (PMID 21962230, 2011). "The GAD1, HIST1H3E, PCDHA8, PCDHA13, SIX3 and SST may regulate the progression of glioma." (PMID 21962230, 2011). "In addition, we found that the percentages of promoter methylation in the ANKDD1A and PHOX2B, but not the GAD1, HIST1H3E, PCDHA8, PCDHA13, SIX3 and SST, were associated negatively with the differentiation degrees of human gliomas." (PMID 21962230, 2011).
tumor (3 papers, 2011 to 2023). "Further, we detected the expression of E-cadherin, Pcdha8 and vimentin genes in the xenograft tumor tissues by immunofluorescent staining." (PMID 30531834, 2019).
prostate (1 paper, 2019). "To determine pathophysiological role of the circAMOTL1L-miR-193a-5p-Pcdha8 pathway in prostate tumorigenesis, we established PCa xenograft models by implanting PC3 cells stably overexpressing circAMOTL1L, anti-miR-193a-5p (miR-193a-5p inhibitor), or both into nude mice." (PMID 30531834, 2019).
PCDHA8 also shares sentences with these, for which no sentence is quoted: Alzheimer disease (2 papers); schizophrenia (2); autism spectrum disorder (1); cancer (1).